PGK1 (phosphoglycerate kinase 1)
Diseases named in the same sentence as PGK1 in open-access papers (continued):
Sharing a sentence is not in itself a finding about the gene and the disease.
glioma (39 papers, 2016 to 2025). A benign or malignant brain and spinal cord tumor that arises from glial cells (astrocytes, oligodendrocytes, ependymal cells). "But in glioma, when cells are stimulated by driving factors such as K‐Ras, B‐Raf mutations, PGK1 can activate pyruvate dehydrogenase kinase 1 (PDHK1) phosphorylation, suppressing the tricarboxylic acid (TCA) cycle ultimately promoting tumour growth." (PMID 40534132, 2025). "For instance, TAM-associated PGK1 phosphorylation has shown correlations with glioma grade, patient prognosis, and tumorigenesis." (PMID 38250074, 2023). "The over-expression of CFL1 and PGK1 were also associated with the poor prognosis of glioma patients." (PMID 28903403, 2017). "The multivariate Logistic regression demonstrated that the expression of CFL1 (p < 0.001) and PGK1 (p < 0.001) were associated with radioresistance in glioma." (PMID 28903403, 2017). "In univariate and multivariate Cox regression, the results demonstrated The CFL1 (HR = 3.381, 95% CI = 2.020–5.659, p < 0.001) and PGK1 (HR = 2.509, 95% CI = 1.563–4.030, p < 0.001) over-expression were associated with the glioma progression." (PMID 28903403, 2017). "An abnormally high level of PGK1 is associated with poor prognosis in patients with glioma." (PMID 34221965, 2021). "Even same in gliomas, PGK1, when activated by phosphorylation of CK2α, translocated in the nucleus but interacting with CDC7, participated in DNA replication." (PMID 40534132, 2025). "In patients with glioma, PGK1 expression level is expected to be one of the indicators for evaluating their radiation sensitivity and prognosis." (PMID 40771921, 2025). "In glioma, METTL1 depletion impairs the m7G modification of PGK1 mRNA, leading to a decrease in PGK1 expression, which suppresses both glioma cell glycolysis in vitro." (PMID 41208200, 2025). "The mechanism of action of lncRNA-NEAT1 and PGK1 provides more ideas for the creation of new drugs for the treatment of glioma." (PMID 40110044, 2025). "By contrast, there are relatively few researches on the mechanism of lncRNA-NEAT1 and Phosphoglycerate kinase 1(PGK1) in glioma." (PMID 40110044, 2025). "Hypoxic wt-IDH glioma tissues from patients show a glycolytic phenotype due to the upregulation of PGK1, PKM2, LDHA, SLC16A3, and CA9 via HIF1." (PMID 38786726, 2024). "Regarding the primary-recurrent-secondary (PRS) type, ALDOC and ABAT exhibited decreased expression, while MIF and PGK1 showed increased expression in recurrent and secondary glioma groups." (PMID 38989284, 2024). "The PGK1 T243 phosphorylation alters the PGK1 and substrate affinity, promoting aerobic glycolysis and tumor growth in glioma cells." (PMID 37981718, 2023). "Hypoxia or glutamine starvation in glioma cells promotes the phosphorylation of Ser301 Beclin1 by PGK1 through the mTOR inhibition which promotes the activation of autophagic initiation complex, which contributes to the brain tumoral aggressiveness." (PMID 38139462, 2023). "Neat1 has recently been found to interact with M1 domain of RBP PGK1 and stabilize PGK1, thereby facilitating glioma progression." (PMID 37716986, 2023). "Previous research demonstrated that long noncoding RNA 01060 (lncRNA01060) increases MZF1 translocation into the nucleus and promotes MZF1-regulated c-Myc, HK2, and PGK1 transcription in glioma, facilitating aerobic glycolysis and inducing tumor progression." (PMID 36499054, 2022). "PGK1 phosphorylates proteins involved in physiological processes and is widely expressed in human abnormal states such as cancer cells of glioma, breast cancer, and hepatocellular carcinoma." (PMID 36077431, 2022).
glioma (continued). "Lastly, NEAT1 expression was positively correlated with PGK1 in glioma samples, indicating NEAT1 and PGK1 are potential biomarkers for glioma." (PMID 35123484, 2022). "Recent studies have shown that PGK1 is overexpressed and functions as an oncogene in numerous tumors, including glioma." (PMID 35123484, 2022). "NEAT1 overexpression is essential for PGK1 stability in glioma cells, thus promoting glycolysis of glioma cells." (PMID 35123484, 2022). "NG52 as a PGK1 kinase inhibitor enhances PDH activity by PGK1 inhibition in blocking the glioma growth." (PMID 36077431, 2022). "M1 depletion significantly impaired the effect of PGK1 on proliferation and glycolysis of glioma cells." (PMID 35123484, 2022). "The inhibition of PGK1 and the subsequent suppression of aerobic glycolysis caused by P7C3 inhibited the malignant growth of glioma in vitro and in vivo." (PMID 34221965, 2021). "Taken together, we found that P7C3 down-regulates the protein level and total intracellular kinase activity of PGK1 in glioma cells." (PMID 34221965, 2021). "According to TCGA and CGGA databases, only PGK1 mRNA level is abnormally upregulated in glioma, and the high PGK1 mRNA levels indicate poor median survival in patients with glioma." (PMID 34221965, 2021). "Although the effect of P7C3 on the kinase activity of PGK1 itself has not been determined at present, we demonstrated that P7C3 down-regulates the protein level and total intracellular kinase activity of PGK1 in glioma cells." (PMID 34221965, 2021). "The result showed that P7C3 significantly reduced the protein expression level of PGK1 and PGK2, especially PGK1, in glioma cells, and the reduction in protein level was concentration-dependent." (PMID 34221965, 2021). "Next, we detected total intracellular kinase activity of PGK1 after treating glioma cells with P7C3 for 24 h." (PMID 34221965, 2021). "Taken together, these results suggest that P7C3-PGK1 interaction induced autophagy-lysosome-mediated PGK1 degradation in glioma cells." (PMID 34221965, 2021). "This study revealed that P7C3 suppresses glioma by regulating aerobic glycolysis via directly targeting PGK1." (PMID 34221965, 2021). "By interfering with the expression of LHX9, the tumorigenicity of glioma cells was promoted, an outcome blocked by further interference with PGK1 expression." (PMID 34536269, 2021). "This P7C3-PGK1 interaction accelerated the PGK1 protein degradation and reduced the protein level and total intracellular kinase activity of PGK1 in glioma cells." (PMID 34221965, 2021). "Our study has demonstrated that miR-6869-5p can regulate glioma cell proliferation and invasion by targeting PGK1." (PMID 32565733, 2020). "PGK1 enhances glioma cell proliferation and invasion, while miR-6869-5p prevents glioma cell growth and invasion by downregulating PGK1." (PMID 32565733, 2020). "In this study, we have firstly found that PGK1 can be targetedly regulated by miR-6869-5p in glioma cells." (PMID 32565733, 2020). "To summarize, this study supports that miR-6869-5p is a tumor suppressor in glioma, which regulates glioma cell proliferation and invasion via targeting PGK1." (PMID 32565733, 2020). "Here we show that both The CFL1 and PGK1 expression can be used as prognosis factors for glioma patients, because both The CFL1 and PGK1 over-expression were associated with poor prognosis of radiotherapy cohort and entire followed-up cohort." (PMID 28903403, 2017). "In this study, both CFL1 and PGK1, as influential factors of radiosensibility, were expressed significantly higher in the radioresistant glioma patients." (PMID 28903403, 2017). "The univariate/multivariate Cox proportional hazards model revealed The CFL1 and PGK1 over-expression were the independent prognosis factors of glioma patients." (PMID 28903403, 2017).
glioma (continued). "Subsequently, the correlation of the expression of CFL1 and PGK1 with clinical characteristics was determined using the survival analysis in order to validate the prognosis of post-radiotherapy and overall glioma patients respectively." (PMID 28903403, 2017). "In this clinical research, we further demonstrated that both CFL1 and PGK1 are also over-expressed in radioresistant glioma patients." (PMID 28903403, 2017). "We also found that the over-expression of CFL1 or PGK1 can reduce glioma radiosensibility in vivo and in vitro, respectively." (PMID 28903403, 2017). "We found that Pgk1 levels were markedly reduced at the transcriptional level in both glioma cells and HMDMs when they were pretreated with ACF before they were stimulated with hypoxia." (PMID 27602954, 2016). "More recent functional evidence indicates that METTL1 drives glioma development through m7G‐dependent modification and stabilization of the glycolytic enzyme PGK1 mRNA, which enhances glycolytic activity, promotes cellular proliferation and accelerates tumour growth in vivo." (PMID 41208200, 2025). "More recent functional studies have shown that METTL1 further drives glioma progression by catalysing m7G modification and stabilizing PGK1 mRNA, a glycolysis‐related enzyme, thereby enhancing glycolytic flux, accelerating cancer cells growth and survival in vivo." (PMID 41208200, 2025). "For example, PGK1 is a well-established HIF1a-regulated gene, and its upregulation is more obvious in differentiated glioma cells under hypoxia as compared with matched GSCs58, which is consistent with both a pro-fitness and pro-glycolytic/mesenchymal activity." (PMID 38316783, 2024). "NEAT1 overexpression also promotes glioma progression through the stabilization of PGK1." (PMID 37403043, 2023). "Additionally, it has been associated with high expression levels of Cofilin 1 and PGK1 with radioresistance in GBM patients, suggesting that Cofilin 1 and PGK1 can be used to evaluate glioma radiosensitivity and prognosis." (PMID 38139462, 2023). "This study suggested that blocking PGK1 T243 phosphorylation may be a potential therapeutic target to inhibit aerobic glycolysis and tumor growth in glioma cells." (PMID 37981718, 2023). "In glioma cells, miR-6869-5p regulates glioma cell proliferation and invasion by targeting PGK1." (PMID 37723547, 2023). "In addition, it has been reported that PGK1 stimulates the radioresistance in human glioma cells, upregulates cell proliferation, and increases migration and invasion." (PMID 38139462, 2023). "LncRNA NEAT1 overexpression promotes glioma cell proliferation and glycolysis by stabilizing PGK1." (PMID 37723547, 2023). "NEAT1 promotes glioma proliferation and glycolysis through regulating PGK1." (PMID 35123484, 2022). "Animal studies were performed to analyze the effect of NEAT1/PGK1 on glioma progression." (PMID 35123484, 2022). "NEAT1/PGK1 axis is a candidate therapeutic target for glioma treatment." (PMID 35123484, 2022). "NEAT1 over expression promotes glioma progression through stabilizing PGK1." (PMID 35123484, 2022). "Taken together, NEAT1/PGK1 axis is indispensable for glioma growth." (PMID 35123484, 2022). "We found that PGK1 mRNA levels were higher in high-grade glioma, both in TCGA and CGGA databases." (PMID 34221965, 2021). "In tumor formation experiments, we observed that interference with downstream PGK1 expression almost completely reversed the tumorigenicity caused by the downregulation of LHX9 expression, suggesting that treatment with inhibitors of PGK1 is highly likely to benefit patients with glioma." (PMID 34536269, 2021). "We measured the PGK1 mRNA expression by qRT-PCR after glioma cells were treated with P7C3 for 24 h." (PMID 34221965, 2021). "Taken together, these findings indicate that P7C3 directly targets PGK1 in glioma cells." (PMID 34221965, 2021).
glioma (continued). "Here, we demonstrated that neurogenic compound P7C3 could inhibit glioma malignant progression in vitro and in vivo by regulating aerobic glycolysis via directly targeting PGK1, which leads to declined energy supply." (PMID 34221965, 2021). "Taken together, this study is the first to report that the neurogenic compound P7C3 exhibits an inhibitory effect on malignant growth of glioma in vitro and in vivo, possibly due to its effect on the glycolytic pathway, specifically on PGK1, as the direct target of P7C3 in glioma cells." (PMID 34221965, 2021). "Furthermore, Kaplan–Meier survival analysis of TCGA and CGGA databases showed that patients with glioma and high expression level of PGK1 exhibited a conspicuously poor overall survival compared with patients with low PGK1 expression level." (PMID 34221965, 2021). "This study suggests that PGK1 is very likely to be an important therapeutic target for gliomas." (PMID 34536269, 2021). "Therefore, we explored the clinical data based on TCGA and CGGA databases to investigate the expression level and the clinical relevance of PGK1 in the median survival of glioma patients." (PMID 34221965, 2021). "Negative association was documented between miR-6869-5p and PGK1 in glioma cells, and PGK1 was demonstrated to be a targeted gene of this miRNA by luciferase reporter assay." (PMID 32565733, 2020). "Taken together, miR-6869-5p could prevent glioma cell proliferation and invasion by targeting PGK1 in vitro." (PMID 32565733, 2020). "miR-6869-5p regulated glioma cell proliferation and invasion via targeting PGK1." (PMID 32565733, 2020). "Thus, both CFL1 and PGK1 can be used as promising biomarkers for radiosensibility, prognosis and progression in glioma; and be potential therapeutic targets of glioma as well." (PMID 28903403, 2017). "The multivariate Cox regression in overall survival suggested that CFL1 level or PGK1 level could be the independent prognosis factor for poor prognosis in 113 glioma patients." (PMID 28903403, 2017). "In this study, the level of CFL1 and PGK1 of 113 glioma tissues were measured by ELISA method." (PMID 28903403, 2017). "We previously reported that CFL1 and PGK1 are over-expressed in radioresistant U251 glioma cells." (PMID 28903403, 2017). "The results suggested that as promising indicators, CFL1 and PGK1 could be used to evaluate glioma radiosensibility and prognosis." (PMID 28903403, 2017). "Thus, PGK1 is a promising target candidate for glioma treatment." (PMID 36077431, 2022). "In addition, we transfected glioma cells with full length or M1-depleted PGK1." (PMID 35123484, 2022). "In addition, NEAT1 expression was positively correlated with PGK1 in glioma." (PMID 35123484, 2022). "In addition, CFL1 expression was positively correlated with PGK1 expression in glioma." (PMID 28903403, 2017). "This reduction in PGK1 expression results in slower tumour growth in vivo, underscoring the critical position of METTL1 mediated m7G in glioma." (PMID 41208200, 2025). "A recent study has been found that lncRNA-NEAT1 knockdown significantly reduces glioma cell proliferation and glycolysis, and lncRNA-NEAT1 increases the protein level of PGK1." (PMID 40110044, 2025). "In glioma, when cells are stimulated by hypoxia or EGFR activation, PGK1 can translocated in mitochondria to activate PDHK1 phosphorylation, suppressing the TCA cycle ultimately promoting tumour growth." (PMID 40534132, 2025). "Similar to the TCGA datasets, all 11 genes exhibited WHO grade-dependent expression in glioma samples, with 6 upregulated (LDHA, MIF, NAMPT, PGK1, SAT1, and PLOD2) and 5 downregulated genes (ALDOC, ABAT, ADCY2, GALNT13, and PDE8B)." (PMID 38989284, 2024). "Consistent with the changes in expression, patients with higher expression of LDHA, MIF, NAMPT, PGK1, SAT1, and PLOD2, and lower expression of ALDOC, ABAT, ADCY2, GALNT13, and PDE8B showed poorer survival rates in all glioma samples." (PMID 38989284, 2024).
glioma (continued). "In glioma tissues, lncRNA NEAT1 specifically interacts with PGK1 to block the ubiquitination and degradation of PGK1." (PMID 37723547, 2023). "NEAT1 and PGK1 expression levels were positively correlated in glioma tissues, indicating NEAT1 and PGK1 are potential biomarkers for predicting glioma patients prognosis." (PMID 35123484, 2022). "We demonstrated that P7C3 is an important regulator of energy metabolism in glioma cells, suggesting that P7C3 regulates aerobic glycolysis by directly targeting PGK1." (PMID 34221965, 2021). "In this study, we investigated novel functions of LHX9 in gliomas and LHX9 regulation of PGK1 and glycolysis." (PMID 34536269, 2021). "CHX, which is a de novo protein synthesis inhibitor, was added to treat the glioma cells, in addition to 50 μM P7C3, and the protein level of PGK1 was detected every 3 h by western blotting." (PMID 34221965, 2021). "To understand the mechanism by which P7C3 reduces the protein level and glycolytic enzyme activity of PGK1 in glioma cells, we first examined the specific interaction between P7C3 and PGK1 using streptavidin affinity assay." (PMID 34221965, 2021). "In addition, miR-6869-5p could prevent glioma cell proliferation via targeting PGK1." (PMID 32565733, 2020). "To establish this model, we transfected GL261 murine glioma cells with a plasmid that carries the murine MGMT gene under a mouse medium-strength promoter (i.e., the murine phosphoglycerate kinase 1 promoter)." (PMID 30413113, 2018). "By using 2D-HPLC-MS/MS method, we found that both PGK1 and CFL1 are abundantly expressed in the radioresistant glioma tissue from patients." (PMID 28903403, 2017). "Collectively our results indicate that over-expression of PGK1 and CFL1 can be closely related to glioma radiosensibility." (PMID 28903403, 2017). "Our results show that ACF treatment interferes with HIF-1α -mediated pathways thereby reducing the hypoxia-induced overexpression level of PGK-1 and VEGF in glioma cell lines, both downstream targets of HIF-1α." (PMID 29097800, 2017). "The Kaplan-Meier survival analysis was used to describe the survival curves of the CFL1 and PGK1 over-expression groups and low-expression groups within each WHO grade II, WHO grade III and WHO grade IV gliomas." (PMID 28903403, 2017). "This safe antibacterial dye induces cell death and apoptosis in several glioma cell lines, targets HIF-1α–mediated pathways, and decreases the level of PGK1, VEGF and HIF-1α in vitro and in vivo." (PMID 29097800, 2017). "Moreover, IDH1 wild-type gliomas displayed a significantly increased expression of glycolytic enzyme genes (LDHA, HK2, PGAM2, PGK1, PKM, TIGAR) compared to IDH1-mutant gliomas as shown in heatmaps." (PMID 33493139, 2021). "In recent studies, NG52 was shown to target the kinase activity of PGK1 and reverse the Warburg effect by inhibiting the phosphorylation of PDHK1 at residue Thr338 site and enhancing the activity of pyruvate dehydrogenase (PDH) in glioma cells." (PMID 34277429, 2021). "Nonetheless, we did not investigate the effect of miR-6869-5p/PGK1 on cancer cell metabolism in glioma." (PMID 32565733, 2020). "For instance, PGK1 promotes glycolysis-driven aggressiveness in gastric and colorectal cancers; P4HA1 regulates collagen remodeling and hypoxia adaptation in breast and lung cancers; and SLC7A11/xCT contributes to ferroptosis resistance in pancreatic, glioma, and prostate cancer models." (PMID 41562911, 2025). "Our study shows that high motility gliomas expressing Cx43 differ from their parental counterparts by the upregulation of MMP3, osteopontin, aldo-keto reductase family 1 member B10 (ARK1B10), and to a lesser degree SERPINE2 (2.5-fold, P = 0.03), and phosphoglycerate kinase 1 (2.4-fold, P = 0.04)." (PMID 30941001, 2019).